ELMO1 (engulfment and cell motility 1)
Diseases named in the same sentence as ELMO1 in open-access papers (continued):
Sharing a sentence is not in itself a finding about the gene and the disease.
bone disorder (1 paper, 2021). "Second, mechanistic studies identify a larger ELMO1-dependent signaling network, with many of the genes and proteins linked to ELMO1 being independently associated with bone disorders and osteoclast function in humans and in mouse models." (PMID 34404802, 2021).
nervous system tumor (1 paper, 2020). "Among them, SFN and ELMO1 have been widely reported to associate with nervous system tumor process." (PMID 32528944, 2020).
ELMO1 also shares sentences with these, for which no sentence is quoted: renal fibrosis (3 papers); chronic kidney disease (2); acute kidney injury (1); acute myeloid leukemia (1); adenocarcinoma (1); amyloidosis (1); asthma (1); autism spectrum disorder (1); colon cancer (1); colorectal cancer (1); Crohn disease (1); diabetic retinopathy (1); follicular carcinoma (1); Fuchs' dystrophy (1); gastric adenocarcinoma (1); gastric atrophy (1); gastrointestinal tumors (1); hay fever (1); Huntington disease (1); hypothyroidism (1); immunodeficiency disease (1); multiple sclerosis (1); nephrotic syndrome (1); Noonan syndrome (1); Obesity (1); oropharyngeal squamous cell carcinoma (1); papillary thyroid carcinoma (1); primary biliary cholangitis (1); rhabdomyosarcoma (1); schizophrenia (1).
A further 5 diseases each share a sentence with ELMO1 in 1 paper.